TOR1AIP2 (torsin 1A interacting protein 2)
Description:
Required for endoplasmic reticulum integrity. Regulates the distribution of TOR1A between the endoplasmic reticulum and the nuclear envelope as well as induces TOR1A, TOR1B and TOR3A ATPase activity.
Synonyms: IFRG15; LULL1; NET9
Tractability: Small molecule: a structure with a bound ligand is known. Antibody: UniProt predicts a signal peptide or a membrane-spanning region. PROTAC: ubiquitination databases record sites on it; its protein half-life has been measured.
Gene: Protein-coding gene on chromosome 1 (179,839,967 to 179,883,034, reverse strand). Ensembl gene ENSG00000169905.
Subcellular location: Endoplasmic reticulum membrane; Nucleus membrane
Subcellular location (Human Protein Atlas): Endoplasmic reticulum
Gene Ontology:
Molecular function: ATPase activator activity; ATPase binding; protein binding
Biological process: endoplasmic reticulum organization; positive regulation of ATP-dependent activity; protein localization to nuclear envelope; membrane organization
Cellular component: endoplasmic reticulum; membrane; endomembrane system; endoplasmic reticulum membrane; nuclear membrane
Genetic constraint (gnomAD): Loss-of-function variants: 19 observed, 34.09 expected, observed/expected ratio (o/e) 0.56, 90% interval 0.39 to 0.82. The upper end of that interval is the gene's LOEUF score, 0.82, which puts it in group 3 of 6, group 1 being the genes least tolerant of losing a copy. Missense variants: 445 observed, 570.66 expected, observed/expected ratio (o/e) 0.78, 90% interval 0.72 to 0.84. Synonymous variants: 212 observed, 219.52 expected, observed/expected ratio (o/e) 0.97, 90% interval 0.86 to 1.08.
Homologues: Orthologues: chimpanzee TOR1AIP2 (99% identical), macaque TOR1AIP2 (95% identical), pig TOR1AIP2 (72% identical), guinea pig TOR1AIP2 (71% identical), mouse Tor1aip2 (69% identical), rat Tor1aip2 (69% identical), tropical clawed frog tor1aip2 (31% identical), zebrafish si:dkeyp-82a1.6 (26% identical), zebrafish zgc:112962 (25% identical). Paralogues in human: TOR1AIP1 (39% identical).
Diseases named in the same sentence as TOR1AIP2 in open-access papers:
TOR1AIP2 is named in the same sentence as 6 diseases in open-access papers, as found by Europe PMC text mining. Sharing a sentence is not in itself a finding about the gene and the disease.
TOR1AIP2 shares sentences with these, for which no sentence is quoted: acute myeloid leukemia (1 paper); Dystonia (1); Legionella infection (1); liver steatosis (1); myelodysplastic syndrome (1); steatosis (1).